ANXA2 (annexin A2)
Diseases named in the same sentence as ANXA2 in open-access papers (continued):
Sharing a sentence is not in itself a finding about the gene and the disease.
glioma (continued). "GSEA of the GSE4412 demonstrated a positive association between expression of hypoxia pathway signature genes and high ANXA2 or OSMR expression in glioma specimens." (PMID 32248843, 2020). "The annexin A2 pseudogenes (ANXA2P1, ANXA2P2, and ANXA2P3) are significantly upregulated in glioma and are associated with adverse outcome of glioma patients." (PMID 31681595, 2019). "ANXA2P2 was positively correlated with genes that are related to glioma proliferation, invasion and angiogenesis, such as ANXA2, CD44, IL6, MMP14, MMP9, and VEGFA." (PMID 31681595, 2019). "Other anti-ANXA2 mAbs demonstrated the ability to reduce tumor burden in ovarian, breast and glioma cancer mouse models." (PMID 29568351, 2018). "ANXA2 expression was also positively correlated with glioma histologic grades and patients’ survival." (PMID 29291003, 2017). "Analysis of TCGA dataset, the OS of glioma patients with high expression of ANXA2 and its pseudogenes were significantly worse than that with low expression (all P<0.0001)." (PMID 29291003, 2017). "Tracing glioma progression in rodent brain, researchers found that the ANXA2 knockdown group were tumor size decreased and tumor progression slowed." (PMID 29291003, 2017). "In this study, for the first time, we found that high expression of ANXA2 pseudogenes were correlated with the poor OS of glioma patients." (PMID 29291003, 2017). "In this study, we evaluated ANXA2 protein expression in a cohort of glioma patients, finding a strong correlation with tumor aggressiveness and patient survival." (PMID 27429043, 2016). "In particular, glioma patients with “Very Low” ANXA2 IHC score (< 25° percentile) show a significantly prolonged PFS and OS when compared with remaining “ANXA2 High” patients." (PMID 27429043, 2016). "To evaluate the impact of ANXA2 expression on glioma aggressiveness, we firstly performed ANXA2 IHC on a series of 89 gliomas." (PMID 27429043, 2016). "Here, we show that ANXA2 is significantly over-expressed in GBM in three independent cohorts of patients and that ANXA2 expression can be considered as an independent prognostic factor in glioma." (PMID 27429043, 2016). "Altogether, these findings suggested that ANXA5, STAT1, CD44, CAV1, MAPT, and ANXA2 might play a vital role in the pathogenesis of gliomas." (PMID 40607003, 2025). "Finally, six genes (ANXA5, STAT1, CD44, CAV1, MAPT, and ANXA2) with the highest degree values were selected as the hub genes for glioma by using the cytoHubba plugin for expression level and prognosis analyses." (PMID 40607003, 2025). "For ANXA5, STAT1, CD44, CAV1, and ANXA2, LGG patients with high expression possessed a worse overall survival, while low expression of MAPT was associated with poor overall survival among patients with primary gliomas." (PMID 40607003, 2025). "Hence, the mechanism of how ANXA5, STAT1, CD44, CAV1, MAPT, and ANXA2 contributed to the gliomas still need further research." (PMID 40607003, 2025). "Generally, these results suggested that ANXA5, STAT1, CD44, CAV1, MAPT, and ANXA2 might play a critical role in the pathogenesis of glioma, suggesting that the hub genes might be a promising biomarker of glioma." (PMID 40607003, 2025). "In summary, a systematic bioinformatics analysis of DEGs demonstrated that ANXA5, STAT1, CD44, CAV1, MAPT, and ANXA2 might serve as potential biomarkers and therapeutic targets for glioma." (PMID 40607003, 2025). "In addition, ANXA2 acts as a potential biomarker for immune infiltration and prognosis of cancer, as well as a potential immunosuppression marker in glioma." (PMID 38542485, 2024). "Moreover, the robust interaction between ANXA2 and B7‐H3 transcripts in four glioma cells compared to U373MG was verified by RIP‐qPCR." (PMID 39048916, 2024). "ANXA2, as a downstream gene of bufalin, was reported to interact with mitochondria, leading to disruption of the mitochondrial division/fusion balance and induction of glioma cell apoptosis." (PMID 37841425, 2023).
glioma (continued). "Notably, ANXA2-induced GPC1 overexpression, in turn, caused a sustained upregulation of c-Myc, leading to enhanced glioma cell proliferation." (PMID 33712571, 2021). "Collectively, these studies support the contribution of ANXA2 to promoting the proliferation of glioma cells, and the overexpression of ANXA2 was sufficient to further increase the proliferation of glioma cells, which already expressed high levels of exogenous ANXA2." (PMID 33712571, 2021). "According to the results above, ANXA2 is mainly involved in the inflammatory response in glioma." (PMID 34675316, 2021). "However, previous studies of ANXA2 in glioma have mostly focused on GBM, and most of them were in vitro studies." (PMID 34675316, 2021). "In addition, further studies about the exact effects of ANXA2 on prognosis and immunosuppression for gliomas via single-cell RNA sequencing are currently in progress." (PMID 34675316, 2021). "We found that ANXA2-induced glioma cell proliferation in a c-Myc-dependent manner." (PMID 33712571, 2021). "Then we explored the prognostic value of ANXA2 in glioma with Kaplan–Meier curves." (PMID 34675316, 2021). "Because our in vitro results confirmed that ANXA2 promoted proliferation by regulating GPC1, we speculated that GPC1 overexpression in glioma may be attributed to the dysregulated expression of ANXA2." (PMID 33712571, 2021). "All these results suggest that it is possible to use ANXA2 as a target for the treatment of glioma, which may reduce the immunosuppression in glioma and improve the overall prognosis of glioma patients, especially HGG patients." (PMID 34675316, 2021). "Similarly, the intracellular delivery of anti-ANXA2 antibody inhibited the cellular loss of ProTα-EGFP, resulting in the redistribution of ProTα throughout C6 glioma cells." (PMID 33807671, 2021). "Recent studies have shown that ANXA2 is important in the development of many cancers, while its role in glioma-related immune response remains unclear." (PMID 34675316, 2021). "Therefore, our results suggest that glioma with high expression of ANXA2 tends to have more infiltrating immune cells, especially immunosuppressive immune cells." (PMID 34675316, 2021). "Besides, we utilized tissue microarrays (TMAs) and immunohistochemistry to demonstrate that glioma patients with both high expression of ANXA2 and GPC1 tended to have higher rate of tumor recurrence and shorter overall survival (OS)." (PMID 33712571, 2021). "ANXA2-based treatment may be an important potential strategy for the comprehensive management of glioma." (PMID 34675316, 2021). "ANXA2 also regulates glioma cell proliferation via the STAT3‐cyclin D1 pathway." (PMID 34047479, 2021). "In this study, we also analyzed the biological function of ANXA2 in glioma." (PMID 34675316, 2021). "miR-1 could decrease the expression of EGFR, PCR1, PCR2, and p-JNK by targeting ANXA2 and Met, thus inhibiting the growth of glioma cells and tumor angiogenesis and reducing the invasiveness of glioma cells." (PMID 34540663, 2021). "Previous studies demonstrated a potential role for ANXA2 in glioma." (PMID 30898167, 2019). "According to above findings, ANXA2 might serve as an independent prognostic biomarker for glioma patients." (PMID 29291003, 2017). "It was found that glioma patients with low ANXA2 and ANXA2 pseudogenes expression could benefit more from chemotherapy and radiotherapy." (PMID 29291003, 2017). "In gliomas, ANXA2 was down-regulated in glioma cells induced by docosahexaenoic acid (DHA)." (PMID 29291003, 2017). "In addition, the over-expression of ANXA2 was attributed to glioma angiogenesis, migration and invasion in vitro rather than proliferation and adhesion." (PMID 29291003, 2017). "Indeed we confirmed a strong up-regulation of Anxa2 in angiogenic xenografts compared to invasive ones, as well as a significant increase in Anxa2 expression in high grade gliomas (grade III and IV) compared to low grades (grade I and II)." (PMID 23874576, 2013).
glioma (continued). "Likewise, ANXA2, which has been isolated in EVs from glioma cell lines and patients, is an important mediator of EV-cell interactions able to promote tumor angiogenesis and the circADAMTS6/ANXA2/NF-κB axis plays an important role in accelerating GBM growth in a hypoxic microenvironment." (PMID 38607010, 2024). "Therefore, inhibition of ANXA2 in gliomas may offer a novel therapeutic strategy and may serve as a possible target in the management of GBM patients." (PMID 38639785, 2024). "Therefore, the combination of ANXA2-targeting and antiangiogenic therapy may be an effective treatment for glioma." (PMID 34675316, 2021). "In conclusion, the overexpression of ANXA2 promotes proliferation of glioma cells by forming a GPC1/c-Myc positive feedback loop, and ANXA2 together with its downstream target GPC1 could be a potential “combination biomarker” for predicting prognosis of glioma patients." (PMID 33712571, 2021). "Furthermore, we demonstrated that the overexpression of ANXA2 could obviously increase the proliferation of U118 glioma cells, which express higher levels of endogenous ANXA2 than the normal human astrocyte cell line NHA (data not shown)." (PMID 33712571, 2021). "However, all these increases could be effectively reversed by a specific inhibitor of c-Myc, 10058-F4, indicating that c-Myc is a key modulator in ANXA2-induced glioma cell proliferation." (PMID 33712571, 2021). "However, other studies, for example in glioma, suggest that not only tetrameric, but also monomeric AnxA2 might serve as a strategy to develop it as a vaccine adjuvant to increase anti-tumour immunity." (PMID 33810523, 2021). "In addition, the involvement of AnxA2 in glioma angiogenesis was highlighted by the demonstration that tumors in wild-type mice displayed significantly higher microvascular density and more dilated blood vessels than tumors in Anxa2-/- mice." (PMID 32575495, 2020). "Furthermore, as a consequence of its interaction with S100A10, ANXA2 can serve as a binding protein for procathepsin B on the surface of breast tumor and glioma cells, which may further facilitate tumor invasion and metastasis." (PMID 24591759, 2014). "Studies of the effect of MeICT on the expression of mRNA MMP-2, annexin A2 and FOXM-2, which are key molecules in the development and invasion of glioma, have shown a significant decrease in the expression of mRNA annexin A2 and FOXM1." (PMID 36902061, 2023). "In gliomas, CTSB can bind to ANXA2 and induce the expression of vascular endothelial growth factor C, TGF-β, and MMP9 to promote angiogenesis." (PMID 36076905, 2022). "We also found that ANXA2 is highly expressed in known malignant glioma molecular phenotypes, such as IDH wild-type and mesenchymal subtype gliomas." (PMID 34675316, 2021). "The data suggest that ANXA2 induces a positive feedback loop involving GPC1 and c-Myc to amplify the proliferation of glioma cells." (PMID 33712571, 2021). "Intriguingly, a positive relationship between ANXA2 and GPC1 was demonstrated at both the mRNA and protein levels in glioma tissues." (PMID 33712571, 2021). "To examine whether ANXA2 associates with S100A13, the cargo protein mediating stress-induced non-classical release under serum-free conditions, we first performed a pull-down assay using the lysates of C6 glioma cells expressing Strep-tagII-S100A13 in the absence or presence of 100 μM of Ca2+." (PMID 33807671, 2021). "Then, the relationship between ANXA2 and GPC1 was investigated by scatter plot analysis, revealing a significant positive correlation between the ANXA2 and GPC1 mRNA levels in the glioma samples (Pearson’s correlation, n = 90, r = 0.878, P < 0.001)." (PMID 33712571, 2021). "The overexpression of both ANXA2 and GPC1 in tumors was reconfirmed by western blot analyses of 6 paired glioma samples selected from the 90 glioma cases." (PMID 33712571, 2021).
glioma (continued). "Most importantly, the combination of ANXA2 and its downstream target GPC1 can be used for improved prognostic evaluation in glioma patients." (PMID 33712571, 2021). "In 90 tumors (Cohort 1), we found that both ANXA2 and GPC1 were more highly expressed at the mRNA level in the glioma samples than in the peritumoral tissues." (PMID 33712571, 2021). "However, the role of ANXA2 in glioma immune escape remains unknown." (PMID 34675316, 2021). "The ANXA2 and GPC1 mRNA expression of 90 paired glioma samples in Cohort 1 was measured by qRT-PCR analysis." (PMID 33712571, 2021). "Annexin A2, which is identified as another CTX target, is involved in cell migration in a series of glioma cells including U87-MG cells." (PMID 30949052, 2019). "Cox regression analyses suggested that ANXA2, ANXA2P1 and ANXA2P2 were the independent prognosis factors for gliomas." (PMID 29291003, 2017). "To investigate the significance of ANXA2 and ANXA2 pseudogenes in diffuse gliomas, we have analyzed the gene expression profiles of glioma samples in GSE4290 that is the independent glioma gene expression dataset." (PMID 29291003, 2017). "Future work will address the efficacy of ANXA2 peptide fusions alone and in combination with established TLR agonists to induce synergy in preclinical models of glioma as observed in other vaccines." (PMID 26885373, 2016). "The protein-protein interaction (PPI) network analysis showed that ANXA5, STAT1, CD44, CAV1, ANXA2, and MAPT may serve as candidate biomarkers in glioma diagnosis." (PMID 40607003, 2025). "We believe that the illustration of ANXA2/NSUN2/YBX1 regulatory axis is a prerequisite to address the complicated pattern of B7‐H3 in glioma, which again highlights the problem of immunotherapy not being universally effective in the cancer population." (PMID 39048916, 2024). "This transcript is stably expressed in all glioma cells but never translated into protein nor affected by ANXA2." (PMID 39048916, 2024). "TM-601 specifically binds to glioma cells but not normal brain tissues and is found to bind to the surfaces of Panc-1 cells as well, depending on the level of annexin A2 expression." (PMID 37444498, 2023). "We subsequently studied the expression of ANXA2 and GPC1 in clinical glioma samples." (PMID 33712571, 2021). "To evaluate the association of S100A13 and ANXA2 induced by serum-free conditions in C6 glioma cells, we adopted the in situ PLA technique, which could amplify the fluorescent signal owing to the interaction between S100A13 and ANXA2." (PMID 33807671, 2021). "All these results indicated that ANXA2 increased the expression of GPC1 via c-Myc and that the upregulated GPC1 further promoted the c-Myc level, forming a positive feedback loop, which eventually led to enhanced proliferation of glioma cells." (PMID 33712571, 2021). "Immunocytochemistry for ANXA2 was performed without permeabilization in siRNA-treated C6 glioma cells." (PMID 33807671, 2021). "Immunoblot analysis result showing that S100A13, but not ANXA2, is lost in C6 glioma cells under serum-free conditions is noteworthy." (PMID 33807671, 2021). "When EGFR and Annexin A2 proteins are simultaneously highly expressed in human glioma cells, the role of the MAPK signaling pathway is significantly enhanced, promoting the aggressive growth of human glioma cells." (PMID 34376212, 2021). "In the present study, we found that ANXA2 increased the expression of GPC1 via c-Myc and that the upregulated GPC1 further promoted the c-Myc level, forming a positive feedback loop, which eventually led to enhanced proliferation of glioma cells." (PMID 33712571, 2021). "Three annexin A2 pseudogenes, including ANXA2P1, ANXA2P2, and ANXA2P3, are significantly upregulated, along with their parent gene annexin A2 (ANXA2), which is correlated with poor survival outcome of glioma patients." (PMID 33995499, 2021).
glioma (continued). "ANXA2 increased the expression of GPC1 via c-Myc and the upregulated GPC1 further promoted the c-Myc level, forming a positive feedback loop, which eventually led to enhanced proliferation of glioma cells." (PMID 33712571, 2021). "Considering the crosstalk between ANXA2 and GPC1, we further determined whether coexpression of ANXA2 and GPC1 could act as a predictor of glioma prognosis." (PMID 33712571, 2021). "Finally, we assessed the clinical significance of ANXA2 and OSMR expression on tumor growth and patient prognosis by analyzing the REMBRANDT, TCGA, and Chinese Glioma Genome Atlas (CGGA) dataset." (PMID 32248843, 2020). "Overexpression of ANXA2 and CDK6 has previously been reported in canine gliomas and CMT cell lines." (PMID 30517191, 2018). "Subsequent multivariate analysis results revealed that in addition to increasing age, KPS, grade and histology, high expression of ANXA2, ANXA2P1 and ANXA2P2 (HR: 1.883, P=0.002; HR: 2.444, P<0.001; HR: 2.053, P=0.001) were also the independent prognosis factors for survival of glioma samples." (PMID 29291003, 2017). "In glioma, the expression of ANXA2 was higher in tumor tissue than in non-neoplastic tissues, and was correlated with mesenchymal and metastatic phenotype of glioblastomas." (PMID 29291003, 2017). "ANXA2 and its pseudogenes expression were remarkably increased in glioma tissues compared with non-tumor controls (all P<0.001)." (PMID 29291003, 2017). "To validate our results, we next retrieved ANXA2 gene expression values from GSE4290 and GSE7696 glioma patients cohorts confirming a significant over-expression of ANXA2 transcript in gliomas relative to control tissues and its progressive increase with tumor grade." (PMID 27429043, 2016). "ANXA2 protein is highly expressed in human high grade, but not in low grade, primary gliomas tissues." (PMID 24591759, 2014). "Our findings agree with two recent reports, showing that TM601 affects certain tumor type cells (including glioma) and vascular endothelial cells in a similar way (binds to annexin A2 and inhibits cell migration), but not the other normal human cells." (PMID 21838899, 2011). "Notably, ANXA2 was shown not to be expressed in U373MG cells, whereas ANXA2 was robustly expressed in all glioma specimens in vivo." (PMID 39048916, 2024). "By contrary, over‐expression of ANXA2 failed to determine the choice of 4Ig or 2Ig in glioma cells." (PMID 39048916, 2024). "When we attempted to perform the pull-down assay using C6 glioma cell lysates and Strep-tagII-S100A13, a member of the S100A family in the absence of Ca2+, ANXA2 dimer was detected, while in the presence of 100 μM Ca2+, higher amounts of ANXA2 dimer and β-actin were detected." (PMID 37371039, 2023). "Finally, we utilized a tissue microarray (TMA) and immunohistochemistry to demonstrate that combined indexes of ANXA2 and GPC1 could improve the evaluation of prognosis in glioma patients." (PMID 33712571, 2021). "Furthermore, univariate and multivariate analyses revealed that in addition to WHO grade and age, the combination of ANXA2 and GPC1 (ANXA2/GPC1) was an independent prognostic factor for TTR (P < 0.001, HR = 3.575, respectively) and OS (P = 0.001, HR = 2.174, respectively) in glioma patients." (PMID 33712571, 2021). "Nevertheless, whether GPC1, the key regulator of glioma cellular proliferation, is regulated by ANXA2 has not yet been studied." (PMID 33712571, 2021). "Additionally, down-regulation of ANXA2, ANXA2P1 and ANXA2P2 might contribute to the improvement of the OS for glioma patients who received chemotherapy and radiotherapy." (PMID 29291003, 2017). "Moreover, from the transcription profile of B7‐H3, it could be seen that the changes of RNA were largely consistent with the protein in these four glioma cell lines, implying that ANXA2 might affect the process of RNA splicing rather than translation." (PMID 39048916, 2024).